INS (insulin)
Diseases named in the same sentence as INS in open-access papers (continued):
Sharing a sentence is not in itself a finding about the gene and the disease.
diabetes (continued). "Sixty toddlers and preschoolers with T1D with mean age of 3.53 ± 1.17 years (range, 2–6) and mean diabetes duration of 9.37 ± 1.85 months were randomly assigned into three equal groups; group A received insulin degludec, group B received insulin glargine, and group C were on NPH." (PMID 36800034, 2023). "Emerging research suggests that open-source automated insulin delivery (AID) may reduce diabetes burden and improve sleep quality and quality of life (QoL)." (PMID 38096018, 2023). "Insulin serves as an important regulator of nutrient homeostasis and a lack of its effects, either due to beta cell failure or resistance in peripheral tissues, or both, results in diabetes mellitus, which affects more than 537 million people worldwide." (PMID 37701894, 2023). "It was observed that a 240 mg/kg HNCP administration decreased the blood glucose levels by 44.5% after 120 min and increased insulin secretion by 142.0% in STZ-induced diabetes mice, which were significantly higher than those by peptides from red deer antlers (about 30%)." (PMID 37888453, 2023). "Thus, the pattern of glycemic effects induced by PDE4 inhibitors is very different, compared to the chronic elevation of blood glucose levels resulting from impaired insulin secretion and/or signaling as a result of diabetes." (PMID 36834669, 2023). "Although multimorbid patients with diabetes in our study were more often on dietary control and insulin therapy compared with patients with diabetes only, more patients in the multimorbid diabetes group had abnormal blood glucose and HbA1c levels as well as occurrences of hypoglycemia." (PMID 37081950, 2023). "The study showed the interest of Polish patients in receiving pharmaceutical care services in diabetes (such as medicines use reviews, patient education on diabetes, insulin administration, and training in the use of glucose meters or lancing devices) and also proved the high need for them." (PMID 36673701, 2023). "Notably, until the early 1990s, only three classes of drugs were available to treat diabetes – insulin, SUs and metformin." (PMID 36845885, 2023). "This may be because patients who inject insulin to control diabetes have a worse blood glucose status, often accompanied by serious complications." (PMID 37185411, 2023). "Adipokines control insulin sensitivity and secretion, contributing to the etiology of diabetes." (PMID 37047011, 2023). "However, in the DR group, we observed distinct correlations between age, blood pressure, HDL, glycated hemoglobin, ALT, duration of diabetes, and insulin usage with the prevalence of DR." (PMID 38174078, 2023). "Direct evidence of the adverse effects of insulin on lung function was supported by a greater than 15% decrease in FEV1 in 1.3% of patients with type 1 diabetes and 5% of patients with type 2 diabetes mellitus following administration of inhaled insulin as therapy for diabetes." (PMID 36837831, 2023). "Additionally, special circumstances such as intravenous insulin therapy, concomitant therapy with glucocorticoids and use of diabetes technology during hospitalization are discussed." (PMID 37101046, 2023). "Reducing glucose fluctuation is important for patients with chronic conditions, such as diabetes, cardiovascular diseases, and obesity, because decreased glycaemic excursions are beneficial for improving insulin sensitivity, oxidative stress, and endothelial dysfunction." (PMID 37950240, 2023). "Compared to women without GDM, the risk for diabetes is explained by their increased insulin resistance and decreased insulin secretion." (PMID 37891561, 2023). "Consequently, the insulin secretion associated with TRPM5 increased and prevented hyperglycemia in high fat diet induced diabetes mice." (PMID 36770924, 2023). "Diabetes mellitus was seen in 7 (11%) patients, of whom 5 (8%) were insulin-dependent." (PMID 35838916, 2023).
diabetes (continued). "Hyperglycemia may be due to poor cellular susceptibility to insulin (insulin resistance) or type 2 diabetes mellitus (T2DM), as well as insufficient secretion of insulin by the pancreas (type 1 diabetes mellitus)." (PMID 38139019, 2023). "However, LRYGB patients still had higher rates of diabetes (insulin-dependent 12.1% versus 6.5%, P < 0.01; non-insulin dependent 19.4% versus 16.4%, P < 0.01) and hypertension (48.3% versus 45.5%, P < 0.01)." (PMID 36708467, 2023). "This concept had been proposed for the sustained release of insulin to treat diabetes." (PMID 36674821, 2023). "Public diabetes service attenders were more likely to use insulin treatment (71.1% vs. 41.3%, p = 0.001), dipeptidyl peptidase-4 inhibitors (DPP4i) (44.7% vs. 21.3%, p = 0.002), and glucagon-like peptide-1 receptor agonists (GLP-1 RA) (13.2% vs. 2.6%, p = 0.002)." (PMID 37152098, 2023). "In this study, greater insulin use could be attributed to older age, greater comorbidities, and a longer duration of diabetes of more than 10 years." (PMID 38074026, 2023). "PTP1B is a negative regulator of insulin signaling and is a therapeutic target for diabetes." (PMID 37763235, 2023). "Literature data indicate that SeNPs produced by biochemical methods (most often by the reduction of sodium selenite with glutathione in the presence of bovine serum albumin (BSA)) raise the insulin concentration in the blood serum in mice with diabetes mellitus." (PMID 38138613, 2023). "Therefore, insulin treatment is often required for patients with diabetes and liver damage, given that many oral antidiabetic medications are not readily available for use in these patients due to associated increases in the risk of adverse reactions." (PMID 37852976, 2023). "One of the most prevalent metabolic diseases in the world, Type 2 diabetes mellitus (T2DM), is predominantly caused by the coincidence of two key factors: the faulty pancreatic beta-cell (β-cell) production of insulin and insulin resistance in insulin-sensitive tissues." (PMID 37764820, 2023). "In our longitudinal six-year study of adults with and without T1D, habitual fiber intake revealed a significant but modest inverse association with HbA1c and a positive association with estimated insulin sensitivity in adults without diabetes." (PMID 37960272, 2023). "Past studies have shown that in diabetics, reduced insulin levels lead to a disorder in insulin signaling, excessive deposition of hyperphosphorylated tau, and ultimately atrophy of the hippocampus and parahippocampal region, resulting in a series of clinical symptoms." (PMID 37255749, 2023). "The risk of diabetes requiring insulin therapy among children with CAs has not previously been examined in a large sample, in multiple regions/countries using a standardised methodology." (PMID 36869270, 2023). "The prevention of diabetes in various models of insulin resistance is recognized from changes in the liver, adipose tissue, and skeletal muscle, and animal studies consistently show that resveratrol improves insulin action." (PMID 37241737, 2023). "It is speculated that hepatic IR in diabetes is likely a result of the impaired physiologic insulin secretion experienced." (PMID 37446104, 2023). "According to NICE guidelines, women with diabetes may be advised to use metformin as an adjunct or alternative to insulin during pregnancy, when the likely benefits from improved blood glucose control outweigh the potential for harm." (PMID 36327019, 2023). "Additionally, senescence of m6A-regulated β-cells promotes the development of diabetes by reducing β-cell proliferative capacity and decreasing insulin secretion." (PMID 37394885, 2023). "Finally, one mother expressed her concern about control and autonomy related to her diabetes management as:“I told my Endo[crinologist], you know, ‘I know that normal protocol is to go on IV Insulin." (PMID 37131168, 2023).
diabetes (continued). "Evidence from our previous research which was carried out on the same study population suggests that in the age group of 65+ years, there has been a marked increase in the prevalence of diabetes-related nephropathy, for which non-insulin therapy is counter-indicated." (PMID 36901500, 2023). "T1DM, or insulin-dependent diabetes, is a type of diabetes that is caused by a lack of insulin is one of the most common metabolic disorders in children." (PMID 36770873, 2023). "However, there are no drugs for antidiabetic use that have been proven to be effective in reducing vascular resistance to insulin, the most likely origin of type 2 diabetes mellitus." (PMID 37686345, 2023). "Diabetes and polyneuropathy, with insulin and pregabalin requirements, were also diagnosed." (PMID 36827238, 2023). "Patho-mechanistically, diabetes-induced exacerbated discharge of the sympathetic, renin-angiotensin aldosterone systems, as well as resistance to insulin, and increased insulin blood level (hyperinsulinemia), are predisposing pathological factors to hypertension." (PMID 37055870, 2023). "According to the recent International Society for Pediatric and Adolescent Diabetes 2022 guidelines, technological advances in insulin delivery, glucose monitoring, and, in more recent years, AID systems should be available for all youth with T1D and tailored to individual wishes and needs." (PMID 37511644, 2023). "In summary, patients with preexisting T1DM could be managed with insulin adjustment and use of usual care, including diabetes technology and insulin therapy, during ICI treatment without adverse outcomes related to glycemic control." (PMID 38027216, 2023). "Physical exercise improves β-cell function and insulin sensitivity among pre-diabetics as well as diabetics by increasing free fatty acid oxidation, enhancing skeletal muscle mitochondrial function, reducing lipotoxicity in skeletal muscles and liver and increasing the serum level of adiponectin." (PMID 37818560, 2023). "In contrast, neither study found a difference in whether morning or evening exercise training can contribute to changes in insulin levels in patients with type 2 diabetes mellitus treated with oral hypoglycemic drugs." (PMID 37208462, 2023). "However, in patients who have developed diabetes or other IR phenotypes, the natural cadence of insulin secretion is disrupted." (PMID 37446104, 2023). "There was no significant or clinically relevant difference between groups in baseline characteristics including age, gender ratio, body mass index (BMI), time since diabetes diagnosis, time since the initiation of insulin pump treatment, and insulin daily doses." (PMID 37616289, 2023). "In addition, it is important to promote equitable access to diabetes therapeutics and technology by funding research through public as well as industry sectors, given that technology and insulin manufacturing companies have high annual net incomes." (PMID 38033993, 2023). "Diabetes has been associated with AD, which is not strange considering that insulin plays a crucial function as a neuromodulator." (PMID 37239068, 2023). "Pancreatic beta cells have received particular attention in terms of oxidative stress and iron, not only because of their key role in diabetes but also the fine tuning of their redox systems that is necessary for normal glucose-induced insulin secretion (see Section 5.1 and 48)." (PMID 36137277, 2023). "Following administration of insulin and once BG levels are stable, some inpatients with diabetes are also given metformin while still being monitored in the hospital to determine if oral diabetes medications used to treat type 2 diabetes are effective." (PMID 37291520, 2023). "Moreover, it was suggested that butyrate can improve insulin sensitivity and reduce body fat that subsequently preventing metabolic syndrome, diabetes, and obesity." (PMID 36781602, 2023).
diabetes (continued). "Guidelines recommend that all diabetes patients engage in self-management education and behavior modification, including nutritional therapy, physical activity, appropriate medication and insulin use, hypoglycemia prevention and treatment, and psychological well-being." (PMID 38161783, 2023). "SNP-19 profoundly affects insulin sensitivity as determined by the altered transcriptional regulation, which may increase the likelihood of developing diabetes." (PMID 37813629, 2023). "The small sample size prevented us from establishing the statistical relevance of the correlation between HbA1C levels and the sociodemographic characteristics of the study participants related to insulin administration, diabetes complications, and educational and mental health approaches." (PMID 37628498, 2023). "Such MIR reduction in the high SDI group of T1DM patients may be due to improving diabetes care, accessibility, and increased insurance coverage and availability of drugs such as insulin pens in the country." (PMID 36918650, 2023). "Hence, it is evident that parameters such as the use of insulin, duration of diabetes, patient’s age, pre-operation BMI, HbA1c, and C-peptide levels play a role in T2DM remission." (PMID 37241216, 2023). "Furthermore, the principal mechanisms explaining the link between insulin treatment and poor outcomes among COVID-19 patients with diabetes are unclear; however, there are different explanations for this relationship." (PMID 37048638, 2023). "Insulin is a vitamin so that can cure you from diabetes (F7)." (PMID 37377235, 2023). "Therefore, low expression of the genes of the ECM interaction pathway can result in impairment in post-stimulus insulin signaling, which can lead to the development of insulin resistance and type 2 diabetes mellitus." (PMID 37123284, 2023). "In the pancreas, it may lead to decreased insulin secretion, via decreased stimulatory signal on pancreatic beta cells, thus leading to hyperglycemia and worsening of diabetes." (PMID 37476593, 2023). "Associations were found between MBzP, MiBP, MCPP, MEHP, MEHHP, and ∑DEHP with HbA1c levels, and between DEHP metabolites with higher amounts of insulin, insulin resistance and fasting glucose, reduced glucose control, and β-cell function, suggesting an involvement of phthalates in pre-diabetes." (PMID 37367903, 2023). "Therefore, preoperative identification of glycemic status and diabetes classification in patients planned to undergo TP are important to guide postoperative insulin treatment." (PMID 36860372, 2023). "Peroxisome proliferator-activated receptor-gamma (PPAR-γ) agonists are insulin-sensitising drugs designed for diabetes patients with insulin resistance; furthermore, they can regulate several cellular processes, such as Aβ degradation and the anti-inflammatory response." (PMID 36830783, 2023). "Targeting PPARγ acetylation might be promising for developing insulin sensitizers with improved safety to curb obesity, diabetes, and metabolic decline during aging." (PMID 37408258, 2023). "In terms of diabetes severity, 12.27% (n = 9057) were at an early stage where they received no pharmacological treatment and 14.41% (n = 10 635) were at the most severe stage requiring insulin therapy." (PMID 37105749, 2023). "Astragalus polysaccharide (APS) is a key active ingredient isolated from Astragalus membranaceus that has been reported to be a potential treatment for obesity and diabetes by regulating lipid metabolism and adipogenesis, alleviating inflammation, and improving insulin resistance." (PMID 36670439, 2023). "Moreover, hypertriglyceridemia subsequently causes significant deposition of fat droplets in the islets 32, impairing glucose-induced insulin secretion 33, eventually contributing to the occurrent of diabetes." (PMID 37790852, 2023).
diabetes (continued). "Previous studies found that complete deletion of HNF4A in mice leads to early embryonic death, and specific deletion of HNF4A in mouse pancreatic β cells does not cause diabetes phenotype, despite impaired glucose-stimulated insulin secretion (GSIS)." (PMID 37711893, 2023). "Diabetes is a chronic metabolic disease characterised by elevated levels of blood glucose due to the body’s impaired ability to produce or respond to the hormone insulin." (PMID 38139295, 2023). "These are some of the receptors and drugs that are now being employed in the treatment of diabetes for e.g. Insulin, GLP-1, PPAR’s, Biguanides, Sulphonylureas, Glinides, Thiazolidinediones, Gliptins, α- Glucosidase inhibitors, Amylin analogues, SGLT-2, Dopamine D-2 agonists." (PMID 36782201, 2023). "The percentage of correct answers was respectively 50% for the item “generalities of diabetes”, 32.4% for the item “hypoglycemia and hyperglycemia”, 67.72% for the item “diet”, 37.34% for the item “management of insulin treatment” and 44.97% for the item “SMBG”." (PMID 37777715, 2023). "Autoimmunity to insulin cannot be distinguished from antibodies to exogenous insulin appearing roughly two weeks after the first insulin injection in T1D cases, and therefore samples need to be tested in this window to be useful for diabetes classification or baseline monitoring in trials." (PMID 37256143, 2023). "FOXO isoforms, in response to insulin signaling, are, therefore, important regulators of the hepatic glucose production and the pancreatic β-cells, which demonstrates the importance of these transcription factors in the regulation of insulin sensitivity and diabetes." (PMID 37891184, 2023). "In addition to metabolic diseases, such as diabetes mellitus, insulin is an immunomodulator in the central nervous system (CNS)." (PMID 37345053, 2023). "The median duration of diabetes was 13.7 years; apart from insulin, 57 patients received metformin." (PMID 38027132, 2023). "Indeed, the effect of GLP-1 on insulin secretion is known to be glucose-dependent and has been demonstrated mostly in hyperglycemic diabetics." (PMID 37886000, 2023). "We focused on insulin owing to its direct relationship with diabetes." (PMID 37258547, 2023). "The authors conducted an electronic search for publications in the PubMed/MEDLINE and Google Scholar databases using the keywords “amyloid beta”, “Alzheimer type-3-diabetes”, “intranasal insulin”, “metformin”, “type 2 diabetes mellitus”, “incretins” and “PPARy agonists»." (PMID 37968954, 2023). "Für Fahrzeuglenker mit Diabetes mellitus, die mit blutzuckersenkenden Medikamenten behandelt werden, die zu einer schweren Hypoglykämie führen können, wie Sulfonylharnstoffe, Glinide und Insulin, ist eine besondere Achtsamkeit in Hinblick auf derartige Ereignisse geboten." (PMID 37101052, 2023). "In addition to increased levels of glucose, db/db mice also showed increased levels of HbA1C and elevated levels of plasma insulin, two hallmarks of diabetes." (PMID 37047807, 2023). "If we consider ectopic insulin expression from the position of cellular stress, it is natural to assume the occurrence of extra-pancreatic IPCs not only in diabetes, but also in a wide spectrum of different pathologies, which, in our opinion, is a promising direction of future investigations." (PMID 38019818, 2023). "There is the major interface among insulin and tyrosine kinase to balance the blood glucose in the system and if the concentration of the Fetuin-A will increase in the blood then the insulin resistance may occur in the body and ultimately diabetes." (PMID 36782201, 2023). "Equally, it was shown that the inhibition of PTP1B expression in mice with polygenic insulin resistance (due to dysfunction of the insulin receptor and the IRS protein) improved glucose tolerance and insulin sensitivity and substantially decreased the incidence of diabetes." (PMID 36997321, 2023).